CD27 (CD27 molecule)
Diseases named in the same sentence as CD27 in open-access papers (continued):
Sharing a sentence is not in itself a finding about the gene and the disease.
Autoimmunity (32 papers, 2003 to 2025). The occurrence of an immune reaction against the organism's own cells or tissues. "Subsequently, its loss of tolerance induces pIgR-specific humoral and T cell autoimmunity that produces anti-pIgR autoantibodies and recruits pIgR antigen- specific CD27+ memory B and plasma cells to the hepatic portal tracts." (PMID 36759512, 2023). "Variable changes of other B cell subsets including immature/transitional B cells (CD20+CD10+ and CD20+/IgM+/CD10+), unswitched memory B cells (CD20+/CD27+/IgM+) and B cells associated with autoimmunity (CD19+/CD23low/CD38low) were also observed." (PMID 35095905, 2021). "M‐B subsets (CD19+CD27+CD38‐) are considered a risk factor for autoimmunity because of their low activation threshold." (PMID 32918534, 2020). "IgD+CD27+ unswitched MBCs decrease is an early feature of pSS correlated with serological autoimmunity and disease progression, and represents the loss of a MZ-equivalent endowed with protective functions such as apoptotic clearance, Interleukin-10-mediated B regulatory activity." (PMID 34603334, 2021). "In addition to plasmablasts, CD27− memory B cell responses have been associated with infection and autoimmunity." (PMID 30072990, 2018). "Several reports have implicated CD70/CD27 pathway in autoimmunity." (PMID 23450201, 2013). "The high expression of CD70 can directly High CD70 expression can directly induce CD27+ lymphocyte over-infiltration, while CD27 and CD70 co-stimulation of the pathway can impede Th17 effector cell differentiation and associated autoimmunity." (PMID 38596682, 2024). "Altogether these data support a pathogenic role of CD28+ CD27- TEMRA and EM CD4+ T cells in autoimmunity." (PMID 35185762, 2022). "A unique subset of CD27- B cells harboring memory potential was described in chronic inflammation and suggested to be driven by infections as well as autoimmunity." (PMID 34745084, 2021). "In our patients with autoimmunity, all auto-Abs studied seem to be mainly maintained by short-lived PC, but only a correlation between switched IgG+ mBc and CD27- IgG+ mBc with anti-ds-DNA auto-Abs in SLE patients was found." (PMID 24819618, 2014). "A recent study also demonstrated that CD70/CD27 pathway impedes the differentiation of Th17 effector cells and attenuates accompanying autoimmunity in a mouse model of multiple sclerosis." (PMID 23450201, 2013). "It is more and more acknowledged that γδ T cells might play a role in autoimmunity, in particular CD27- γδ T cells." (PMID 36793723, 2023). "CD27+IgD+ B cells are centrally involved in the processes of innate host defense, but on the other hand, they also represent several features that argue for a role in autoimmunity." (PMID 19419560, 2009). "The CD27 and CD70 costimulatory pathway has been found to inhibit the transcription of the key effector molecules IL-17 and the chemokine receptor CCR6, subsequently attenuates associated autoimmunity, Cancer cells can reprogramme their metabolism to support cell growth and proliferation." (PMID 37732314, 2023). "B cell analysis showed elevated unswitched CD27+ and CD21low cells as well as features of an autoreactive antibody repertoire and presence of secreted autoantibodies, yet no clinical autoimmunity was present." (PMID 39812873, 2025). "Although we assessed changes in naïve and memory CD4+ T cell subsets using CD27 instead of CCR7 as a marker, none of them revealed an association with presence of secondary autoimmunity." (PMID 32539719, 2020). "As the population of CVIDid patients with low CTLA4 + CD27 + Tregs represented a mix of patients with pulmonary inflammation but also other organ-specific autoimmunity (data not shown), abatacept may be efficacious in other CVIDid patients as well." (PMID 34247288, 2021).
Autoimmunity (continued). "Another candidate B-cell subset of relapsing autoimmunity might be CD27+IgD+ non-switched MemB, which according to their surface marker expression are reported to correspond to splenic CD27+IgD+(IgM+) marginal zone B cells in rodents." (PMID 19419560, 2009). "In particular, acquisition of the CD27+CD45RA+ phenotype appears to be a critical checkpoint of late T cell development in the human thymus and may play an important role in the prevention of autoimmunity." (PMID 14575152, 2003). "Certain memory cells lose their CD27 expression and become IgD-, CD27- ‘double-negative’ memory B cells, which are non-dividing, inflammatory cytokine-producing cells that could play a role in autoimmunity." (PMID 36389812, 2022).
myeloma (32 papers, 2011 to 2026). "Since we did not observe differences in frequencies of the potential MM-reactive CD27(−)T cells between studied groups of patients, this may suggest that the suppression of the anti-myeloma potential of T cells is caused by the accumulation of exhausted T lymphocytes unable to control tumor growth." (PMID 35807007, 2022). "Moreover, CD27 activates both the classical and alternative nuclear factor-κB pathways and the under-expression of CD27 in CD-1 myeloma subgroup is reported to be associated with a lower NF-κB signature when compared to CD-2 myeloma subgroup." (PMID 25831238, 2015). "In congruence with prior research indicating that heightened PD-L1 expression is integral to the tumor microenvironment, we delved deeper into the composition of immune infiltrates in myeloma and its interplay with CD27 expression." (PMID 38504180, 2024). "As expected, compared with the DMSO group, CD27 expression was increased in myeloma cells, PERK and ATF4 mRNA and protein expression were correspondingly increased." (PMID 38504180, 2024). "Another example is CD27, which is heterogeneously expressed in patient myeloma cells and where low levels have been found to correlate with poor prognosis." (PMID 39567630, 2024). "In conclusion, the diminishing expression of CD27 in monoclonal gammopathy underscores the potential role of CD27 in the malignant evolution of myeloma." (PMID 38504180, 2024). "The observations highlighted a discernible decline in CD27 expression levels concomitant with the progression of myeloma, corroborating the outcomes derived from flow cytometry." (PMID 38504180, 2024). "While prior research has emphasized the clinical significance of CD27 in plasma cells of MM patients, its potential role within myeloma’s microenvironmental T cells and its broader mechanistic implications in MM remain uncharted territories." (PMID 38504180, 2024). "CD27, one of the top genes of this signature, has been previously discussed in MM literature, but has been reported to have variable expression in myeloma cells, increased expression in MGUS, and a correlation with prognosis." (PMID 36396631, 2022). "In multiple myeloma, Kaplan–Meier analysis showed that patients with high CD27 expression had a longer overall survival time than patients with low CD27 expression." (PMID 33766042, 2021). "We anticipate that anti-CD27 can be used to enhance the effects of other direct-targeting mAbs such as anti-CD38 in myeloma and anti-EGFR in solid tumors, and we are in the process of investigating this." (PMID 29198913, 2017). "These clonogenic myeloma cancer stem cells show normal memory B cell phenotypes (i.e., CD138negCD20+CD27+)." (PMID 24252328, 2013). "Although CD27 is detected on normal plasma cells, its expression is significantly reduced with the progression of multiple myeloma (MM)." (PMID 22182738, 2011). "Moreover, we demonstrate the feasibility of targeting CD70 in myeloma using NK cells engineered with a chimeric antigen receptor (CAR) incorporating the CD70 cognate receptor CD27 and IL-15 (CAR27/IL-15)." (PMID 41144785, 2026). "In conclusion, CD27 may affect myeloma cell activity through the PERK-ATF4 signaling pathway, which in turn affected the survival of MM patients." (PMID 38504180, 2024). "This leads to the inference that the adverse prognosis observed in patients with heightened CD27 expression in MM could be attributed to an augmented presence of myeloid-derived suppressor cells and macrophages in the myeloma microenvironment." (PMID 38504180, 2024). "The Cluster of Differentiation 27 (CD27) is aberrantly expressed in multiple myeloma (MM) -derived." (PMID 38504180, 2024). "GSEA further suggested that CD27 might influence the myeloma microenvironment via the nuclear factor-κB (NF-κB) signaling cascade." (PMID 38504180, 2024). "Likewise, CD27 is also particularly important for prognosis in multiple myeloma and clear cell renal cell carcinoma." (PMID 35392242, 2022).
myeloma (continued). "Expression of CD70 and CD27 is also detected on malignant plasma cells in multiple myeloma, where CD27 decreases with increasing progression of the disease and its absence might even be a prognostic factor for high-risk disease." (PMID 34991665, 2022). "Taken together, we have shown that MM-derived EV promote immunosuppression by modulating the phenotype of lymphoid cells with an increase in the expression of the IC PD-1 and CTLA-4, accompanied by a decrease in CD27 expression, thus facilitating myeloma cell escape and progression." (PMID 35874665, 2022). "Nonetheless, CD27 is identified on a rare B cell population that may be responsible for the generation and maintenance of the characteristic Reed-Sternberg cells of Hodgkin lymphoma and on a population suggested to be multiple myeloma stem cells." (PMID 34991665, 2022). "In untreated myeloma patients, a slight increase of CD27−/28− T-cells to a mean fraction of 13.6% (± 4.13) and decrease of CD27+/CD28+ T-cells to a mean fraction of 75.2% (± 4.53) in comparison to healthy donors could be demonstrated (p=0.02 and p=0.013, respectively)." (PMID 33363008, 2020). "Additionally, higher myeloma‐reactive T‐cell ratios of CD27–:CD27+ were prognostic for PFS, which may be reflective of reactivation after treatment with lenalidomide and subsequent transplant." (PMID 33049118, 2020). "To evaluate myeloma memory B cells, we identified clusters of memory B cells that were either unswitched (UM1–4 clusters; CD19+, IgM+, IgDhet, CD20+, CD22+, and CD27+) or switched (SM1–3 clusters; IgM+, IgD–, CD27het, IgG+, and IgA+)." (PMID 36752202, 2023). "For example, enrichment of a CD27+CD45RO-CD8+ population in apheresis products prior to CAR T generation predicts remission for both CLL and multiple myeloma." (PMID 35603165, 2022). "Although the exact role and phenotype of these subpopulations in myeloma are unknown, but variously, these cells are thought to include CD138- with memory B‐cells (CD19+/CD27+), CD38high/CD138+ cells, and side population (SP) cells." (PMID 35646666, 2022). "To evaluate if other antigens might be preferable to BCMA for the detection of myeloma EVs, we evaluated 15 samples from 5 of the 10 patients treated with Belantamab (cycles 1 to 3) and quantified EVs with the following antigens: CD23, CD27, CD38, CD56 and CD138." (PMID 38039414, 2023). "To assess the total clonal myeloma population via flow cytometry, we first characterized the expression of CD138, CD38 and other markers that differentiate myeloma cells (not shown: CD19, CD27 and CD45)." (PMID 38001595, 2023).
rheumatoid arthritis (31 papers, 2005 to 2025). A chronic, systemic autoimmune disorder characterized by inflammation in the synovial membranes and articular surfaces. "KEGG pathway analysis further revealed the enrichment of DE genes in the chemokine signaling pathway, cytokine–cytokine receptor interaction pathway, TNF signaling pathway, and rheumatoid arthritis pathway, confirming the pathogenic features of CD27+IgD+ B cells in RA." (PMID 29628928, 2018). "In rheumatoid arthritis (RA), the CD27 IgD naïve B cell subset produces IL-6, and both HIF-1α and IL-6 are co-expressed in RA patient B cells." (PMID 40791591, 2025). "In our previous work, comparing two types of early untreated rheumatoid arthritis patients, we identified a somewhat similar CD27+ CD4 T cell subset." (PMID 37306812, 2023). "The subset that scored the highest in innateness, CD4+HLA-DR+CD27− T cells, are the precise subset that is most expanded in rheumatoid arthritis and correlate with treatment response." (PMID 30737409, 2019). "The observation that the return of CD27 + (memory B cells) coincides with the return of disease activity in rheumatoid arthritis prompted use of CD27 + B-cell monitoring to guide retreatment of NMO." (PMID 29511864, 2018). "Correlation analysis of CD27+IgD+ B cells with rheumatoid arthritis patient clinical manifestations." (PMID 29628928, 2018). "CD27+ memory B cells have a greater capacity to produce TNFα than naive B cells in patients with rheumatoid arthritis (RA)." (PMID 27044386, 2016). "Related studies of adult rheumatoid arthritis (RA) have noted differences in Thelper and HLA-DR + CD27- cytotoxic T-cell activity in the synovium, while also characterizing excessive myeloid activation in ACPA-negative cases." (PMID 36793127, 2023). "Interestingly, CD28+ CD27- TEMRA and EM CD4+ T cells expressing Th1- and cytotoxicity-associated genes have also been described to be increased and associated with higher damage in rheumatoid arthritis patients." (PMID 35185762, 2022). "CD27-IgD- double-negative (DN) B cells lacking the conventional memory marker CD27 are reported to be part of the memory compartment, however, only scarce data is available for rheumatoid arthritis (RA)." (PMID 25888920, 2015). "Recently, CD27 and IgD double-negative-2 B cells (DN2 B cells), akin to atMBCs, have been also implicated as the major precursor of ASCs and associated with the pathogenesis in patients with rheumatoid arthritis (RA)." (PMID 38426103, 2024).
breast cancer (27 papers, 2010 to 2025). A primary or metastatic malignant neoplasm involving the breast. "the IVW method results showed that CD45RA- CD4+ %CD4+ (p-value:1.37×10−6), CD8dim %T cell (p-value:4.62×10−43), BAFF-R on IgD+ CD38- unsw mem (p-value:6.93×10−5), CD27 on PB/PC (p-value:2.72×10−18) lowered the risk of breast cancer." (PMID 38327747, 2024). "Compared to CD27+IgG- B cells, the CD27+IgG+ B cells markedly elevated expression of IFN-γ, which was consistent with our finding that CD27 on PB/PC reduces the risk of breast cancer." (PMID 38327747, 2024). "Atypical memory B cells (CD19+CD27‒IgM‒) showed a significant increase in the peripheral blood of patients with breast cancer compared to the control group." (PMID 38702630, 2024). "In this study, the frequency of CD19+CD27‒IgM‒ aMBCs was significantly higher in the peripheral blood of patients with breast cancer than in the control group." (PMID 38702630, 2024). "Clusters 1–6 mostly lacked expression of Cd27 mRNA, whereas Cluster 7 was enriched in cells expressing Cd27, indicating that lung CD27− γδ T cells are highly responsive to mammary tumors." (PMID 36480166, 2023). "In breast cancer, incubation of CD27+CD21lo/med B cells with CD4+ T cells promoted Th1 responses and suppressed Treg responses." (PMID 34374937, 2022). "The fourth generation of FRα-targeted CAR-T cells containing the costimulatory domains CD28, 4-1BB, and CD27 demonstrated superior therapeutic efficacy in breast cancer due to the o combined benefits of the three costimulatory domains." (PMID 35935930, 2022). "IgD- CD27- AC and CD27 on IgD+ CD38- unsw mem (memory B cells) were identified as potential mediators of the causal relationship between critically ill COVID-19 and HER2-positive breast cancer." (PMID 40355230, 2025). "Moreover, critically ill COVID-19 exhibited causal relationships with CD27 on IgD + CD38- unsw mem, and the latter also demonstrated a positive causal relationship with the risk of HER2-positive breast cancer." (PMID 40355230, 2025). "Therefore, a positive causal relationship was identified between critically ill COVID-19 and IgD- CD27- AC (atypical memory B cells), with the latter also exhibiting a positive causal relationship with the risk of HER2-positive breast cancer (P < .05)." (PMID 40355230, 2025). "Therefore, we compared the transcriptome data of Cluster 1 from WT mice with Clusters 1–6 from tumor-bearing KB1P mice to determine which genes are differentially regulated in CD27− γδ T cells by mammary tumors." (PMID 36480166, 2023). "To recapitulate the systemic increase of IL-1β and IL-23 in mammary tumor-bearing mice, we stimulated CD3+ T cells isolated from lungs of WT mice in vitro with these cytokines and examined tumor-associated protein expression in CD27− γδ T cells." (PMID 36480166, 2023). "Although CD27 polymorphisms associated with infectious diseases have not been identified, rs2267966 was reported to be associated with a decreased risk of breast cancer in a northern Chinese population." (PMID 33308178, 2020). "The mRNA expression showed that all five genes were differentially expressed in breast cancer: C3, GFPT, and GMFG were significantly down-regulated, while CD27 and HLA-DPB1 were significantly up-regulated." (PMID 37287069, 2023). "The CD27 molecule was confirmed to enhance the killing effect of Trop2-targeted CAR-T cells and to prolong their survival time in breast cancer." (PMID 35935930, 2022). "In CD8 T cells, higher CD27 and CD28 expression was observed in controls compared to women with breast cancer (p = 0.001 and p < 0.0001, respectively)." (PMID 30061900, 2018). "Particularly, the identification of IgD- CD27- AC and CD27 on IgD + CD38- unsw mem as mediators signals towards intricate immune responses catalyzed by severe COVID-19 that might augment oncogenic processes in HER2-positive breast cancer." (PMID 40355230, 2025).
breast cancer (continued). "We then used machine learning methods to perform feature selection and reduction, which generated a clinical-friendly scoring system consisting of 5 genes (C3, CD27, GFPT2, GMFG, and HLA-DPB1) that could be used to predict clinical outcomes in breast cancer patients." (PMID 37287069, 2023). "NKG2D CAR-T cells with CD27 or 4-1BB costimulatory signaling molecules could promote the expansion and self-enrichment of CAR-T cells without the presence of IL-2, effectively enhancing the ability to recognize and eliminate breast cancer." (PMID 35935930, 2022). "Although a role has not been assigned to this cell population in breast cancer, previous studies in other tumor types suggest that CD27 co-expression on the surface of CD8+ T cells directly correlates with the ability of these CD8+ T cells to mediate tumor regression." (PMID 31417550, 2019).